RSPO4 (R-spondin 4)
Description:
Activator of the canonical Wnt signaling pathway by acting as a ligand for LGR4-6 receptors. Upon binding to LGR4-6 (LGR4, LGR5 or LGR6), LGR4-6 associate with phosphorylated LRP6 and frizzled receptors that are activated by extracellular Wnt receptors, triggering the canonical Wnt signaling pathway to increase expression of target genes. Also regulates the canonical Wnt/beta-catenin-dependent pathway and non-canonical Wnt signaling by acting as an inhibitor of ZNRF3, an important regulator of the Wnt signaling pathway.
Synonyms: C20orf182; dJ824F16.3; CRISTIN4
Tractability: Antibody: its Gene Ontology location is reachable by antibodies, with high confidence; UniProt places it where antibodies can reach, with medium confidence; UniProt predicts a signal peptide or a membrane-spanning region.
Gene: Protein-coding gene on chromosome 20 (958,452 to 1,002,372, reverse strand). Ensembl gene ENSG00000101282.
Subcellular location: Secreted
Pathways (Reactome):
Signal Transduction: Regulation of FZD by ubiquitination
Gene Ontology:
Molecular function: protein binding; signaling receptor binding
Biological process: nail development; positive regulation of Wnt signaling pathway; positive regulation of canonical Wnt signaling pathway; limb development
Cellular component: extracellular region; non-collagenous component of interstitial matrix
Genetic constraint (gnomAD): Loss-of-function variants: 24 observed, 25.43 expected, observed/expected ratio (o/e) 0.94, 90% interval 0.68 to 1.33. The upper end of that interval is the gene's LOEUF score, 1.33, which puts it in group 5 of 6, group 1 being the genes least tolerant of losing a copy. Missense variants: 333 observed, 296.56 expected, observed/expected ratio (o/e) 1.12, 90% interval 1.03 to 1.23. Synonymous variants: 141 observed, 112.94 expected, observed/expected ratio (o/e) 1.25, 90% interval 1.09 to 1.44.
Homologues: Orthologues: chimpanzee RSPO4 (98% identical), macaque RSPO4 (95% identical), dog RSPO4 (87% identical), pig RSPO4 (87% identical), guinea pig RSPO4 (82% identical), mouse Rspo4 (82% identical), rat Rspo4 (82% identical), zebrafish rspo4 (44% identical). Paralogues in human: RSPO2 (41% identical), RSPO1 (40% identical), RSPO3 (37% identical).
Diseases named in the same sentence as RSPO4 in open-access papers:
RSPO4 is named in the same sentence as 28 diseases in open-access papers, as found by Europe PMC text mining. Sharing a sentence is not in itself a finding about the gene and the disease. The quoted sentences say what the papers report.
Anonychia (12 papers, 2011 to 2025). Aplasia of the nail. "The mutation in the RSPO4 gene, encoding R-spondin 4, was associated with rare conditions: anonychia and hyponychia, manifested with absence or severe hypoplasia of fingernails and toenails." (PMID 33799809, 2021). "Study expanded RSPO4 mutations related with anonychia/hyponychia to 17 and all of them were found located in the first three exons encoding a signal peptide and the highly conserved furin-like cysteine-rich domains." (PMID 25945348, 2015). "These structures provide a framework for studying disease mutations, e.g., those in RSPO4 causing congenital Anonychia." (PMID 24349440, 2013). "With this report, the total number of RSPO4 mutations associated with anonychia/hyponychia is expanded to 17, all of which are located in the first three exons encoding a signal peptide and the highly conserved furin-like, cystein-rich domains." (PMID 23234511, 2012). "For example, alterations in RSPO4 activity have been reported to cause anonychia in humans, whereas disruption of Rspo2 or Rspo3 in mice affects development of several different systems (skeletal, respiratory or placenta defects)." (PMID 21297984, 2011). "R-spondin-4 mutations cause anonychia (absence or severehypoplasia of all fingernails and toenails, OMIM 206800)." (PMID 21533022, 2011). "Mutations in the RSPO4 can underlie inherited anonychia/hyponychia." (PMID 40428299, 2025). "Anonychia-related mutations in RSPO4 support the importance of the observed interface." (PMID 24349440, 2013). "In addition to RSPO4 mutations in anonychia/hyponychia, it was recently shown that mutations in FZD6 cause isolated autosomal recessive nail dysplasia (MIM 614157)." (PMID 23234511, 2012). "Anonychia/hyponychia congenita is a rare autosomal recessive developmental disorder characterized by the absence (anonychia) or hypoplasia (hyponuchia) of finger- and/or toenails frequently caused by mutations in the R-spondin 4 (RSPO4) gene." (PMID 23234511, 2012). "Furthermore, our findings indicate that the RSPO4 missense variant p.M1I is a polymorphism despite its previous association with anonychia in two Pakistani siblings." (PMID 23234511, 2012). "Murine models with conditional Rspo2 [R-spondin 2, which, like RSPO4 (R-spondin 4), belongs to the R-spondin protein family] knockouts recapitulate human anonychia, further supporting pathogenicity." (PMID 40620857, 2025). "Results related to Rspo4 gene targeting are not available yet; however, in humans, mutations affecting RSPO4 function are associated with anonychia, the absence of finger- and toenails." (PMID 29316729, 2018). "Expression of Rspo4 has been shown to play a key role during nail development and mutations in Rspo4 gene results into absence of the nails in humans termed as anonychia/hyponychia congenita." (PMID 25276837, 2014). "Congenital mutations in RSPO4 resulted in anonychia with the absence of all fingernails and toenails in humans, and RSPO4 mutations preferentially clustered in the furin-like cysteine-rich domains." (PMID 23217106, 2012).
breast carcinoma (3 papers, 2022 to 2023). "In breast cancer patients, RSPO2, RSPO3, and RSPO4 overexpression has been reported, which is associated with hormone receptor‐negative tumor status and for RSPO2 also with reduced patient survival." (PMID 36106661, 2022). "As WNT signaling activation had been found to overexpress in breast cancer, particularly in triple-negative breast cancer, the role of RSPO4 involved in GC progression remained unelucidated." (PMID 35480879, 2022). "In their study, western blotting showed that the expression of PER1 and PER2 decreased in the rhythm group, whereas the expression of breast carcinoma amplified sequence 4 (BCAS4), tubulin beta-2B chain (TUBB2B), and Roof Plate-Specific Spondin-4 (RSPO4) increased in the breast cancer group." (PMID 38074657, 2023). "Overexpression of RSPO2, RSPO3, and RSPO4 has been reported in breast cancer patients, in particular in triple‐negative tumors, where enhanced RSPO2 expression was associated with reduced metastasis‐free survival." (PMID 36106661, 2022).
hyponychia congenita (3 papers, 2012 to 2022). "In one girl, anonychia congenita caused by a compound heterozygous variant of the R-spondin-4 gene (RSPO4) was diagnosed." (PMID 36421794, 2022).
nail disorder (3 papers, 2019 to 2025). A disease involving the nail. "Clinically, pathogenic mutations in RSPO4 (R65W, Q70R, and G72R) linked to hereditary nail disease are mapped to homologous positions in other RSPO subtypes, underscoring the functional necessity of these conserved residues." (PMID 40428299, 2025). "Pathogenic variants of five genes (RSPO4, FZD6, HPGD, PLCD1, and COL7A1) have been reported to cause congenital pure nail disorders, among which FZD6 (frizzled class receptor 6) and RSPO4 are responsible for most of the cases." (PMID 36421794, 2022). "The genes associated with human hereditary nail disorders are listed as HPGD, RSPO4, PLCD1, COL7A1 and FZD6." (PMID 30642273, 2019).
esophageal squamous cell carcinoma (2 papers, 2021 to 2026). Esophageal squamous cell carcinoma (ESCC) is a type of esophageal carcinoma (EC) that can affect any part of the esophagus, but is usually located in the upper or middle third. "RspO4 can activate the Wnt/β-catenin signaling pathway and promote the progression of esophageal squamous cell carcinoma." (PMID 34026368, 2021).
asthma (1 paper, 2026). "We also found a significant association between RSPO4 methylation and diagnosis age (p < 0.001), neoplasm histologic grade (p < 0.05), Karnofsky performance score (p < 0.001), ethnicity (p < 0.005) and asthma history (p < 0.05) in patients with brain lower grade glioma." (PMID 41522353, 2026).
chondrocalcinosis (1 paper, 2021). An acute episode of pain, swelling, and redness, sometimes associated with fever. "Other potential genes that were studied in patients with DISH and chondrocalcinosis (DISH/CC) include R-spondin 4 (RSPO4), LEM domain-containing 3 (LEMD3), and protein phosphatase 2 regulatory subunit beta delta 2 (PPPR2RD)." (PMID 33923907, 2021).
Congenital anonychia (1 paper, 2021). "Single-cell RNAseq with 11,541 cells from 4 extra digits revealed nail-specific mesenchymal and epithelial cell populations, characterized by RSPO4 (major gene in congenital anonychia) and SPINK6, respectively." (PMID 34099859, 2021).
liver fibrosis (1 paper, 2021). "This study also identified a group of significant taxa associated with liver fibrosis and its regression to normal status by treatment with RSPO4-CRISPR." (PMID 33603089, 2021). "In the present study, we knocked out the RSPO4 gene in rats with CCl4-induced liver fibrosis using the Clustered Regularly Interspaced Short Palindromic Repeats (CRISPR) system." (PMID 33603089, 2021). "A noteworthy finding was that the mRNA levels of RSPO4, α-SMA, and collagen-I in the CRISPR group are likely to close to those of the control, suggesting RSPO4-CRISPR may be able to reverse the progression of liver fibrosis." (PMID 33603089, 2021). "We found RSPO4-CRISPR relieved liver fibrosis in rats and reversed HSC activation." (PMID 33603089, 2021). "By knocking out RSPO4 gene in fibrotic-liver rat model, they show that it relieved liver fibrosis in rats and restored the microflora composition, highlighting its potential in liver fibrosis treatment." (PMID 33603089, 2021). "Our in vivo and in vitro studies showed that RSPO4-CRISPR effectively represses HSCs activation and relives liver fibrosis in rats." (PMID 33603089, 2021). "In conclusion, this study revealed that RSPO4 gene knockout with the CRISPR system relieves the liver fibrogenesis in rats, and restores dysbiotic gut microbiota related to liver fibrosis to an equilibrium status similar to healthy rats." (PMID 33603089, 2021).
periodontitis (1 paper, 2026). An acute or chronic inflammatory process that affects the tissues that surround and support the teeth. "RSPO4 has been shown to play important roles in nail development, liver fibrogenesis and periodontitis, while its role in cancerous context remains largely unknown." (PMID 41522353, 2026). "RSPO4 is reported to be involved in nail development, liver fibrogenesis and periodontitis 20-22." (PMID 41522353, 2026).
polydactyly (1 paper, 2024). A disease characterized by the presence of polydactyly, including syndromic and non-syndromic forms. "A total of 151 SNP loci significantly correlated with the polydactyly trait were identified through GWAS, and five genes, R-spondin 4 (RSPO4), tensin-3 (TNS3), chloride channel 7 (CLCN7), SLC52A3, and ANGPT4, were annotated to be significantly correlated with polydactyly." (PMID 38612286, 2024).
rectum adenocarcinoma (1 paper, 2026). An adenocarcinoma arising from the rectum. "Methylation analysis using MethSurv also indicated that higher RSPO4 methylation level with specific probes was associated with worse overall survival of patients with rectum adenocarcinoma (READ)." (PMID 41522353, 2026).
tetra-amelia syndrome (1 paper, 2022). "Human genetic studies revealed that RSPO1 is critical for ovarian development, and RSPO2 mutation leads to tetra-amelia syndrome including lung aplasia and a lack of limbs, while RSPO4 is necessary for human nail formation." (PMID 34847079, 2022).
thyroid cancer (1 paper, 2022). "There is no published study showing RSPO4 up-regulation in aggressive thyroid cancer." (PMID 36611933, 2022). "RSPO4 protein and mRNA expression was decreased after BRAF knockout when compared to wild-type in our panel of metastatic and non-metastatic human thyroid cancer cell lines (THJ-16T, 8505C and TPC-1)." (PMID 36611933, 2022).
tumor (5 papers, 2020 to 2026). "To elucidate the molecular mechanisms underlying the tumor suppressive effects of RSPO4, we performed bioinformatic analysis of TCGA CRC dataset." (PMID 41522353, 2026). "The χ2 analysis revealed a significant association between RSPO4 methylation and diagnosis age (p < 0.01), histological type (p < 0.001) and tumor size (p < 0.05) in CRC patients." (PMID 41522353, 2026). "Collectively, based on its frequent silencing/downregulation, loss-of-function mutations, and copy number loss in multiple cancer types, we conclude that RSPO4 is likely a tumor suppressor in human cancers." (PMID 41522353, 2026). "Through cancer epigenomics, we identified RSPO4 as a candidate tumor suppressor with tumor-specific epigenetic inactivation." (PMID 41522353, 2026). "Ectopic RSPO4 expression significantly decreased tumor growth and average tumor weight of LoVo xenografts in nude mice, compared with vector control." (PMID 41522353, 2026). "Knockdown of RSPO4 expression by siRNAs generated an opposite effect in tumor cells by luciferase reporter assay, leading to the activation of canonical and non-canonical Wnt signaling." (PMID 41522353, 2026). "Colony formation assay (CFA) showed that the numbers of colonies were significantly less in tumor cells with ectopic expression of RSPO4 than the vector control, and more colonies were observed with knockdown of RSPO4 expression." (PMID 41522353, 2026). "Considering R-spondins are important regulators of Wnt signaling 62, 63, it would be possible that RSPO4-induced tumor suppressive effects were mediated by Wnt signaling." (PMID 41522353, 2026). "Functional studies showed that RSPO4 inhibited tumor cell proliferation, migration, invasion and stemness, through antagonizing canonical and non-canonical Wnt signaling." (PMID 41522353, 2026). "Anchorage-independent soft agar assay showed that colony numbers were significantly decreased in tumor cells with RSPO4 expression, along with reduced colony size, compared with vector controls." (PMID 41522353, 2026). "We transfected expression plasmids encoding V5-tagged RSPO4 into A549 and KYSE150 tumor cells and examined its subcellular localization by indirect immunofluorescence." (PMID 41522353, 2026). "Levels of total-, phosphorylated- (Ser552) and active β-catenin (i.e. unphosphorylated at Ser33/Ser37/Thr41) as well as the downstream target gene (c-MYC) were also reduced in RSPO4-expressing tumor cells compared with vector control cells." (PMID 41522353, 2026). "In this study, we found that RSPO4 inhibited tumor cell proliferation, metastasis and stemness through suppressing both canonical and non-canonical Wnt/β-catenin signaling, indicating RSPO4 as a Wnt antagonist." (PMID 41522353, 2026). "Taken together, these results indicated that RSPO4 inhibited tumor cell proliferation and metastasis through antagonizing both canonical and non-canonical Wnt signaling." (PMID 41522353, 2026). "RSPO4 drug-conjugates targeting LGR4/5/6 simultaneously generated robust anti-tumor effect 23, 24, implying its tumor suppressive roles in human cancers." (PMID 41522353, 2026). "LoVo cells with stably expressed RSPO4 or control vector were injected into nude mice, with tumor formation efficiency monitored across different time points." (PMID 41522353, 2026). "We treated tumor cells with recombinant human RSPO4 protein and observed its effect at different time points and found that RSPO4 induced an initial increase of β-catenin level within the first hour followed by an attenuated response thereafter." (PMID 41522353, 2026). "Scratch wound healing assays showed that RSPO4-transfected cells had less efficient healing ability than vector control cells, suggesting a suppressive role of RSPO4 on tumor cell migration." (PMID 41522353, 2026).
tumor (continued). "In both tumor cell lines, when RSPO4 was expressed, a significant increase in cells in S phase was observed, with corresponding decrease in cells in G0/G1 phase (p < 0.05); the opposite was observed in tumor cells with RSPO4 knockdown." (PMID 41522353, 2026). "Western blot also detected an opposite effect with RSPO4 knockdown by siRNAs, including increased levels of N-cadherin, vimentin and fibronectin in tumor cells." (PMID 41522353, 2026). "At the molecular level, Western blot showed that RSPO4 expression led to reduced phosphorylation of RhoA (Ser188) in tumor cells." (PMID 41522353, 2026). "Bisulfite genomic sequencing (BGS) detected high density of methylated CpG sites within the region spanning core promoter and exon 1 of RSPO4 in representative tumor cell lines." (PMID 41522353, 2026). "To verify findings from our CpG methylomic study and public database analysis, we examined the expression and methylation of RSPO4 in normal tissues, cancer cell lines and primary tumor tissues." (PMID 41522353, 2026). "The tumor-specific promoter CpG methylation of RSPO4 makes it a potential cancer biomarker and therapeutic target." (PMID 41522353, 2026). "Our study revealed a novel role of RSPO4 as a tumor suppressor through antagonizing Wnt signaling, which provides important implications for development of diagnostic biomarkers and targeted therapy." (PMID 41522353, 2026). "One cell line (KPNSI9S) has a high expression of RSPO3 while six cell lines express RSPO4 at moderate levels, suggesting that they were expressed in tumor cells in the primary tumors." (PMID 39065640, 2024). "Therefore, LGR4/5 and ZNRF3 are required for the suppressive effect of RSPO4 expression on tumor cell migration, invasion and stemness, and RSPO4 exerts these effects through suppressing Wnt signaling." (PMID 41522353, 2026). "As RSPO4 expression inhibits tumor cell proliferation, the slight increase in S phase cells could be explained by the accumulation of cells arrested in this phase, rather than cells actively replicating DNA." (PMID 41522353, 2026). "Taken together, these results suggested that RSPO4 acted as a tumor suppressor in tumor growth." (PMID 41522353, 2026). "A tumor xenograft model was used to investigate whether RSPO4 expression could suppress tumor formation in vivo." (PMID 41522353, 2026). "Therefore, RSPO4 shares similarities with RSPO2 in the mechanism of tumor suppression but with obvious difference." (PMID 41522353, 2026). "We further examined RSPO4 methylation in primary tumor samples." (PMID 41522353, 2026). "To test this hypothesis, we performed immunofluorescence staining and found that nuclear β-catenin levels were reduced in RSPO4-expressing tumor cells compared with vector control." (PMID 41522353, 2026). "We then explored the function of RSPO4 by evaluating its effect on tumor cell growth." (PMID 41522353, 2026). "We assessed whether RSPO4 mitigates tumor cell migration, invasion, stemness through inhibiting Wnt signaling." (PMID 41522353, 2026). "Having demonstrated that loss of RSPO4 can push cells toward a more mesenchymal phenotype, we next performed sphere-formation assay to evaluate the effect of RSPO4 expression on tumor cell stemness, as EMT is known to correlate with stem-like properties in both normal and cancer cell lines." (PMID 41522353, 2026). "Therefore, RSPO4 has a suppressive role on tumor cell migration, invasion and stemness." (PMID 41522353, 2026). "In this study, through methylomic study and database mining, we identified another member of the R-spondin family, RSPO4, as a TSG candidate inactivated by promoter CpG methylation in multiple carcinomas in a tumor-specific way." (PMID 41522353, 2026). "We found that RSPO4 FUm1/2 mutant lost its inhibitory effect on migration and invasion of both LGR4+/LGR5- and LGR4-/LGR5+ tumor cells." (PMID 41522353, 2026).